TMPRSS11A (transmembrane serine protease 11A)
Description:
Probable serine protease which may play a role in cellular senescence. Overexpression inhibits cell growth and induce G1 cell cycle arrest.
Synonyms: ECRG1; HATL1; HESP
Tractability: Antibody: UniProt predicts a signal peptide or a membrane-spanning region; its Gene Ontology location is reachable by antibodies, with medium confidence.
Gene: Protein-coding gene on chromosome 4 (67,909,395 to 67,964,140, reverse strand). Ensembl gene ENSG00000187054.
Subcellular location: Membrane
Gene Ontology:
Molecular function: serine-type peptidase activity; serine-type endopeptidase activity
Biological process: protein processing; proteolysis
Cellular component: plasma membrane; extracellular region; membrane
Genetic constraint (gnomAD): Loss-of-function variants: 43 observed, 48.97 expected, observed/expected ratio (o/e) 0.88, 90% interval 0.69 to 1.13. The upper end of that interval is the gene's LOEUF score, 1.13, which puts it in group 4 of 6, group 1 being the genes least tolerant of losing a copy. Missense variants: 430 observed, 455.4 expected, observed/expected ratio (o/e) 0.94, 90% interval 0.87 to 1.02. Synonymous variants: 150 observed, 152.76 expected, observed/expected ratio (o/e) 0.98, 90% interval 0.86 to 1.12.
Homologues: Orthologues: chimpanzee TMPRSS11A (99% identical), macaque TMPRSS11A (94% identical), rabbit TMPRSS11A (80% identical), dog TMPRSS11A (79% identical), pig TMPRSS11A (78% identical), rat Tmprss11a (65% identical), mouse Tmprss11a (65% identical), guinea pig TMPRSS11A (60% identical), zebrafish st14b (28% identical), zebrafish st14a (27% identical), Drosophila melanogaster Sb (24% identical), zebrafish tmprss15 (23% identical), and 4 more. Paralogues in human: TMPRSS11F (43% identical), TMPRSS11E (42% identical), TMPRSS11B (40% identical), TMPRSS11D (40% identical), HPN (29% identical), TMPRSS6 (28% identical), TMPRSS2 (28% identical), TMPRSS13 (27% identical), ST14 (26% identical), TMPRSS3 (25% identical), TMPRSS15 (24% identical), TMPRSS7 (24% identical), and 5 more.
Diseases named in the same sentence as TMPRSS11A in open-access papers:
TMPRSS11A is named in the same sentence as 16 diseases in open-access papers, as found by Europe PMC text mining. Sharing a sentence is not in itself a finding about the gene and the disease.
TMPRSS11A shares sentences with these, for which no sentence is quoted: Obesity (3 papers); asthma (1); cancer (1); diabetes (1); endothelial dysfunction (1); esophageal carcinoma (1); glioma (1); Hyperglycemia (1); Hypertension (1); infection (1); Insulin resistance (1); lung diseases (1); lymphoma (1); neuroblastoma (1); prostate hyperplasia (1); tumor (1).